ANLN (anillin, actin binding protein)
Diseases named in the same sentence as ANLN in open-access papers (continued):
Sharing a sentence is not in itself a finding about the gene and the disease.
tumor (continued). "The results revealed ANLN upregulation and SLC16A12 and WDR72 downregulation in ccRCC tumor tissues compared to adjacent normal tissues." (PMID 41332473, 2025). "Immunohistochemistry images from the HPA database also manifested that the protein expression levels of ANLN, LY6D, and SERPINB3 are notably higher in PC tumor tissues." (PMID 41427028, 2025). "In oral cancer, ANLN activation leads to phosphorylation of PI3K, mTOR, AKT, and PDK-1, resulting in markedly elevated pathway activity that promotes tumor development." (PMID 41573677, 2025). "In anaplastic thyroid carcinoma, ANLN interacts with RhoA to activate the PI3K/AKT pathway and facilitate tumor progression." (PMID 41573677, 2025). "Research has uncovered the tumor-promoting effects of ANLN in LUAD, indicating its overexpression correlates with a poorer prognosis, potentially due to enhanced tumor metastasis." (PMID 40486872, 2025). "RT‒qPCR was then conducted to compare mRNA expression levels of WDR72, ANLN, and SLC16A12 in adjacent normal and ccRCC tumor tissues." (PMID 41332473, 2025). "Among these, seven genes, namely, RRM2, KIF11, ANLN, CDC20, YWHAZ, DTL, and PCNA, exhibited significantly elevated expression in tumor samples (p ≤ 0.05)." (PMID 41487287, 2025). "Subsequently, utilizing machine learning techniques, we constructed the PIS model, comprising marker genes of CKS1B+ tumours (RHOV, ANLN, DEAR, PSMB7, KRT8, LDHA)." (PMID 38946232, 2024). "Regarding the protein levels of these genes, SLC2A1, MMP14, TOP2A, ANLN, and SLC22A3 exhibited higher expression in tumor samples compared to normal samples." (PMID 37604837, 2023). "An additional scoring (aggression score) system based on the expression of the ANLN and BCL2 genes correlated the ERness score with the tumor grade to predict the intrinsic aggressiveness of the tumors." (PMID 36834918, 2023). "qRT-PCR and IHC showed increased ANLN, RHOV, and KRT6A expression in the LUAD cells and tumor tissues." (PMID 37974107, 2023). "ImageJ software calculated the positivity rate, and the results confirmed that ANLN, RHOV, and KRT6A were all significantly upregulated in the tumor samples." (PMID 37974107, 2023). "Then, based on tumor expression data from TCGA in GEPIA2, we performed correlation analysis to investigate the top 100 ANLN co-expression genes." (PMID 35568883, 2022). "Among the five RMScore genes, four (ANLN, KRT6A, PITX3, and NTSR1) were identified to be upregulated, while CYP17A1 was identified to be downregulated in TCGA-LUAD tumor tissues compared with paired normal tissues." (PMID 35859664, 2022). "Our results suggest that ANLN-201 and ANLN-210 showed subtype-specific overexpressed in tumor cell lines and highly expressed in HNSCC cell lines such as SCC-9." (PMID 34344861, 2021). "Next, we used a box plot to illustrate that ANLN and HIST1H1C are constantly and significantly highly expressed in tumor tissues from all the datasets (GSE28735, GSE62452 and TCGA)." (PMID 32966237, 2020). "ANLN expression was confirmed to be up-regulated in the majority of tumor samples (26/31, 83.87%), while TLE2 was down-regulated in the majority of tumor samples (25/31, 80.64%)." (PMID 31766561, 2019). "We further demonstrated that ANLN knockdown significantly inhibited the levels of EZH2 and LASP1 expression in xenograft tumor models." (PMID 31395079, 2019).
tumor (continued). "In this study, we demonstrated that ANLN contributed to ICC growth via the RhoA/LATS1/YAP1 axis, establishing a link between ANLN and the Hippo pathway, which broadened the understanding of the role of ANLN in tumor." (PMID 41513610, 2026). "The subcutaneous xenograft ICC models demonstrated that simvastatin or verteporfin treatment obviously reduced the tumor volume enhanced by ANLN overexpression, but did not affect the weight of the mice." (PMID 41513610, 2026). "Furthermore, ANLN overexpression has been shown to promote the proliferation of NPC cells in vitro, while ANLN knockdown in xenograft models inhibits tumor growth." (PMID 41573677, 2025). "Furthermore, we established xenograft tumor mouse models by subcutaneous injection of MDA-MB-231 cells with CCNE1 overexpression and ANLN knockdown." (PMID 40346052, 2025). "Furthermore, we analyzed the protein expression levels of ANLN, DCBLD2, LY6D, and SERPINB3 using the UALCAN platform, which were notably upregulated within PC tumor tissues." (PMID 41427028, 2025). "In addition, ANLN and ECT2 expression was strongly correlated in both normal and tumor tissues, which is to be expected due to ECT2 forming a complex with ANLN to regulate cytokinesis." (PMID 38785827, 2024). "In addition, we explored the relationship between TRP-related prognostic features and TME and revealed strong correlations between ANLN, DLGAP5, FAM83A, PTTG1, and RHOV with tumor immune infiltration, immune checkpoints, and substance metabolism pathways." (PMID 39144144, 2024). "Subsequently, stable GBC-SD cells with ANLN silencing and negative control cells were subcutaneously implanted into the armpits of nude mice to establish a subcutaneous tumor transplantation model." (PMID 38398143, 2024). "HCC patient-derived tumor xenograft (PDX) models were also established from four HCC patient tissues, two with high and two with low ANLN m6A modifications, respectively, and employed these to assess the clinical potential of using DZNeP to target m6A modified ANLN." (PMID 36923927, 2023). "By analyzing the relationship between ANLN expression and the quantity of neoantigens, we observed that ANLN expression was positively correlated with LUAD, BRCA, STAD, UCEC, and HNSC, suggesting that ANLN may enhance immunity in some tumor types." (PMID 35340220, 2022). "Finally, we used the ssGSEA method to determine the correlations between ANLN, POLR3G, EHBP1, and ERO1A and 24 types of tumor-infiltrating immune cells." (PMID 35769906, 2022). "To clarify the role of ANLN transcripts in HNSCC, firstly we assessed the expression levels of ANLN splice isoforms in HNSCC tumor tissues and adjacent non-tumor tissues." (PMID 34344861, 2021). "There is not much direct evidence of the relation between ANLN expression and the immune evasion of tumours." (PMID 32560530, 2020). "Following this second hypothesis, we computationally found reliable interactions between UCA1 and the 3′-UTRs of ANLN, BIRC5, IPO7, KIF2A, and KIF23 that overlapped several miRNA-binding sites of tumor-suppressor miRNAs." (PMID 30195762, 2018). "Multivariate Cox regression analysis showed that tumor size (HR = 1.104, P < 0.001), tumor thrombus (HR = 2.059, P = 0.019), tumor nodes (HR = 1.821, P = 0.004), ALT level (HR = 1.004, P = 0.006), and ANLN expression (HR = 1.822, P = 0.003) were independently associated with overall survival." (PMID 30103211, 2018). "While hardly seen in non-tumor tissue, the ANLN positive cells accounted for 12.5% of total cells in tumor tissue (P < 0.001)." (PMID 30103211, 2018). "The relationship between HBV and ANLN expression in HCC development and tumor progression is unknown." (PMID 30103211, 2018). "The top differentially expressed transcripts between tumor and non-tumor were TPX2, DCBLD2 and ANLN which were significantly increased in tumors (T∶N ratio>2.0, P<0.01), and CDO1, DPEP1, C7, ALDH1A1 and NR3C2 which were significantly decreased in tumors (T∶N ratio<0.2, P<0.01)." (PMID 22363658, 2012).
tumor (continued). "Increased ANLN and ECT2 mRNA gene expression was significantly associated with PCa, and Gleason scores using both the TCGA cohort (p < 0.05) and an AA non-malignant/tumor-matched cohort." (PMID 38785827, 2024). "Additionally, immunohistochemical analysis demonstrated a decrease in Ki67 levels in the subcutaneous tumor tissues after ANLN silencing compared to the negative control group." (PMID 38398143, 2024). "Furthermore, DZNeP treatment significantly inhibited the tumor growth of the high ANLN m6A-modified HCC PDX models, while these effects were not evident in the two low ANLN m6A-modified HCC PDX lines." (PMID 36923927, 2023). "There is not much evidence of the direct effects of ANLN on re-educating the tumour microenvironments, but ANLN is a multiple-domain scaffold for many proteins, which suggests that ANLN could indirectly regulate the microenvironment through interactors." (PMID 32560530, 2020). "However, it is not clear whether ANLN ubiquitination is related to tumor progression or treatment; there are no reports indicating whether ANLN is regulated by deubiquitination." (PMID 36526897, 2023). "Furthermore, in the larger cohort II, multivariable cox regression analysis showed that a high nuclear fraction of ANLN was significantly associated with a reduced BCSS and RFS independent of the cell proliferation marker Ki-67, tumor size, hormone receptor status, HER2 status, nodal status and age." (PMID 27863473, 2016). "While the initiating cells in recurrent tumors were mainly related to the cell cycle such as MKI67, CKS2, ANLN, CDC20, CDCA8, CENPF, inflammatory signals no longer drive anti-tumor immunity." (PMID 41601649, 2026). "We validated ANLN and ECT2 mRNA expression in tissue, utilizing the TCGA PRAD and an AA non-malignant/tumor-matched clinical cohort." (PMID 38785827, 2024). "There was a gradually increasing trend based on the protein expression of ANLN from grade I to grade III, while age, weight, and tumor stage groups did not significantly differ given the protein expression of ANLN." (PMID 37007961, 2023). "We observed that two splice variants of ANLN, which were ANLN-201 (ENST00000265748.6, 4731 nt) and ANLN-210 (ENST00000457743.1, 757 nt) were significantly expressed in HNSCC tumor tissues compared to the non-tumor tissues." (PMID 34344861, 2021). "We assessed ANLN and ECT2 expression differences in tumor versus non-malignant tissue." (PMID 38785827, 2024).
adenocarcinoma (3 papers, 2017 to 2025). A common cancer characterized by the presence of malignant glandular cells. "ANLN was significantly upregulated in adenocarcinoma cells compared with healthy lung epithelial cells, and related to the progression of LUAD patients." (PMID 40761262, 2025). "Notably, 4 of the glucose metabolism-related genes, GPI, G6PD, PKM2, and GAPDH and 5 of the cell cycle-related genes, ANLN, PTTG1, CIT, KPNA2, and CDC25A, were significantly down-regulated in EGFR m+ adenocarcinomas, and showed a substantial correlation with SUVmax." (PMID 28422979, 2017).
blood cancer (2 papers, 2022 to 2025). "This discovery provides the first direct evidence linking ANLN abnormalities to the onset of blood cancers and highlights a mechanistically distinct mode of ANLN activation compared with solid tumors." (PMID 41573677, 2025).
kidney disease (2 papers, 2020 to 2021). "Proteins anillin, coded on the ANLN gene, and advillin, coded on AVIL gene, are both F-actin-binding proteins needed for podocyte motility and both have mutations that are associated with kidney disease." (PMID 32708597, 2020).
benign-tumor (1 paper, 2024). "Given our findings, which suggest that low expression of ANLN and ECT2 are associated with increased overall survival, we validated ANLN and ECT2 expression in both the TCGA PRAD cohort and an AA prostate contralateral benign-tumor-matched cohort." (PMID 38785827, 2024).
gastrointestinal tumors (1 paper, 2022). "Additionally, we further confirmed the protein expression of ANLN in gastrointestinal tumors using immunohistochemistry data from the HPA database." (PMID 35568883, 2022).
prostate (1 paper, 2024). "Studies investigating the role of ANLN and ECT2 in prostate carcinogenesis are diminutive." (PMID 38785827, 2024). "Thus, our novel findings lay the foundation to further elucidate the anti-proliferative effects of 1α,25(OH)2D3 in non-malignant prostate maintenance and prostate carcinogenesis by targeting potential survival PCa biomarkers, ANLN and ECT2." (PMID 38785827, 2024).
ANLN also shares sentences with these, for which no sentence is quoted: lung squamous cell carcinoma (3 papers); pancreatic adenocarcinoma (3); adenocarcinoma of the rectum (2); hematological malignancies (2); lymphoid neoplasm (2); malignant melanoma (2); testicular germ cell tumor (2); thymoma (2); uveal melanoma (2); bacterial infection (1); Bartter Syndrome Type 3 (1); Branchio-otic syndrome (1); cavernous cerebral malformation (1); cervical squamous cell carcinoma (1); colon adenocarcinoma (1); colorectal adenoma (1); developmental delay (1); digestive system cancer (1); endometrial carcinoma (1); esophageal cancer (1); HIV-associated nephropathy (1); Hydrocephalus (1); hypopharyngeal carcinoma (1); intrahepatic cholangiocarcinoma (1); invasive ductal carcinomas (1); Joubert syndrome (1); laryngeal carcinoma (1); metastasis (1); mucinous adenocarcinoma (1); neurodegenerative disease (1).
A further 15 diseases each share a sentence with ANLN in 1 paper.